BCL2L11 (BCL2 like 11)
Description:
Induces apoptosis and anoikis. Isoform BimL is more potent than isoform BimEL. Isoform Bim-alpha1, isoform Bim-alpha2 and isoform Bim-alpha3 induce apoptosis, although less potent than isoform BimEL, isoform BimL and isoform BimS. Isoform Bim-gamma induces apoptosis. Isoform Bim-alpha3 induces apoptosis possibly through a caspase-mediated pathway. Isoform BimAC and isoform BimABC lack the ability to induce apoptosis.
Synonyms: BIM; BOD; BimL; BimEL; BimS; BAM
Tractability: Small molecule: a structure with a bound ligand is known; a high-quality ligand is known. Antibody: UniProt places it where antibodies can reach, with medium confidence. PROTAC: UniProt records ubiquitination sites on it; its protein half-life has been measured; a small molecule that binds it is known.
Target class: Ion channel; Other ion channel; Bcl-2 family; Miscellaneous ion channel
Chemical probes: ML214, ML258
Safety:
Unwanted effects reported when the protein is acted on. In parentheses: how it was acted on, where the effect was seen, and who reports it.
osteonecrosis (source: ClinPGx)
osteonecrosis when treated with corticosteroids (source: ClinPGx)
Gene: Protein-coding gene on chromosome 2 (111,119,378 to 111,168,444, forward strand). Ensembl gene ENSG00000153094.
Subcellular location: Endomembrane system; Mitochondrion (Isoform BimEL); Mitochondrion (Isoform BimL); Mitochondrion (Isoform BimS); Mitochondrion (Isoform Bim-alpha1)
Subcellular location (Human Protein Atlas): Mitochondria
Pathways (Reactome):
Disease: Deregulated CDK5 triggers multiple neurodegenerative pathways in Alzheimer's disease models; Signaling by BRAF and RAF1 fusions
Gene expression (Transcription): FOXO-mediated transcription of cell death genes; RUNX3 regulates BCL2L11 (BIM) transcription
Programmed Cell Death: Activation of BIM and translocation to mitochondria; BH3-only proteins associate with and inactivate anti-apoptotic BCL-2 members
Immune System: FLT3 Signaling
Signal Transduction: NRAGE signals death through JNK
Gene Ontology:
Molecular function: protein binding; microtubule binding; protein kinase binding
Biological process: intrinsic apoptotic signaling pathway in response to DNA damage; positive regulation of apoptotic process; positive regulation of fibroblast apoptotic process; positive regulation of protein-containing complex assembly; positive regulation of release of cytochrome c from mitochondria; regulation of apoptotic process; response to endoplasmic reticulum stress; apoptotic process; cellular response to glucocorticoid stimulus; positive regulation of endoplasmic reticulum stress-induced intrinsic apoptotic signaling pathway; positive regulation of IRE1-mediated unfolded protein response
Cellular component: Bcl-2 family protein complex; mitochondrion; BIM-BCL-2 complex; cytosol; mitochondrial outer membrane; cytoplasm; endomembrane system; membrane
Genetic constraint (gnomAD): Loss-of-function variants: 13 observed, 16.81 expected, observed/expected ratio (o/e) 0.77, 90% interval 0.5 to 1.23. The upper end of that interval is the gene's LOEUF score, 1.23, which puts it in group 5 of 6, group 1 being the genes least tolerant of losing a copy. Missense variants: 261 observed, 225.96 expected, observed/expected ratio (o/e) 1.16, 90% interval 1.04 to 1.28. Synonymous variants: 99 observed, 84.5 expected, observed/expected ratio (o/e) 1.17, 90% interval 1 to 1.38.
Homologues: Orthologues: chimpanzee BCL2L11 (100% identical), macaque BCL2L11 (98% identical), pig BCL2L11 (92% identical), rabbit BCL2L11 (90% identical), guinea pig BCL2L11 (88% identical), mouse Bcl2l11 (87% identical), rat Bcl2l11 (85% identical), dog BCL2L11 (65% identical), tropical clawed frog bcl2l11 (54% identical), zebrafish bcl2l11 (22% identical). Paralogues in human: MEI1 (30% identical), SCIMP (8% identical).
Diseases named in the same sentence as BCL2L11 in open-access papers:
BCL2L11 is named in the same sentence as 166 diseases in open-access papers, as found by Europe PMC text mining. Sharing a sentence is not in itself a finding about the gene and the disease. The quoted sentences say what the papers report.
breast carcinoma (38 papers, 2009 to 2025). "In conclusion, this study revealed that rs4900321 and rs7150025 in ATG2B, rs6753785 in BCL2L11, and rs2213181 in c-Kit are associated with early breast cancer prognosis in a Chinese population." (PMID 38690279, 2024). "In addition, rs71801447, which lies in the 3′-UTR of BCL2L11, was associated with BCL2L11 expression and anti-tumor immune response in breast cancer." (PMID 38690279, 2024). "Specifically, BCL2L11 is a tumor suppressor that regulates cell proliferation, metastasis, and chemotherapeutic resistance in breast cancer." (PMID 38690279, 2024). "In support of this assessment, lower levels of BIM (BCL2L11) gene expression were found in ICBP breast cancer cell lines (p = 0.0004) and TCGA tumors (p = 0.0002), and RPPA protein expression was lower in TCGA tumors (p < 0.0001)." (PMID 28446242, 2017). "However, the biological role of RA in miR-30a-5p on BCL2L11 during MDA-MB-231 induced breast cancer stem-like cells (BCSCs) progression and its regulatory mechanism have not been elucidated." (PMID 39239646, 2024). "In addition, elevated expression of the pro-apoptotic protein BCL2-interacting mediator of cell death (BIM)/BCL2L11, a marker of onset of anoikis in breast cancer cells, was detected in suspension cultures of LM-SMARCE1-KD cells, but not in LM-EV cells." (PMID 27495308, 2016). "At least three genes from this list were involved in the formation of carcinomas, including breast carcinoma (CASP8, HSPA4, BCL2L11), prostate carcinoma (BCL2, CASP8, BCL2L11, ATM), and chronic lymphocytic leukemia (BCL2, CASP8, FAS, BCL2L11, BAK1)." (PMID 37298337, 2023).
melanoma (28 papers, 2013 to 2025). A malignant, usually aggressive tumor composed of atypical, neoplastic melanocytes. "This process appears to be reverted upon MAPK pathway inhibition in the presence of TGFβ1, resulting in elevated BCL2L11 protein levels and, consequently, apoptosis induction in melanoma." (PMID 39709491, 2024). "Activation of canonical WNT signaling by the WNT3a ligand or inhibitor of GSK-3β kinase induced apoptosis in melanoma and neuroblastoma cell lines due to the upregulation of the expression of pro-apoptotic gene BCL2L11 in melanoma, and the downregulation of cyclin D1 in neuroblastoma." (PMID 36612190, 2022).
lung carcinoma (23 papers, 2007 to 2025). "The previous study has reported that patients with BCL2L11 deletion polymorphism got a relatively poor efficacy from the osimertinib, which has the directive significance of treatment selection to the young lung cancer group." (PMID 35096611, 2021). "Here we show that up-regulation of the BH3-only polypeptide BIM (also known as BCL2-like 11) correlated with gefitinib-induced apoptosis in gefitinib-sensitive EGFR-mutant lung cancer cells." (PMID 17973572, 2007).
lymphoma (21 papers, 2012 to 2025). A malignant (clonal) proliferation of B- lymphocytes or T- lymphocytes which involves the lymph nodes, bone marrow and/or extranodal sites. "This is consistent with observations that the loss of a single BCL2L11 allele accelerates lymphoma development in Eμ-MYC transgenic mice." (PMID 27490482, 2016). "BCL2L11 functions as a tumor-suppressor gene in diverse types of cancers, such as gastric cancer, lymphoma, and rectal cancer." (PMID 40806148, 2025). "In addition, we showed that both BCL2L11 and PMAIP1 were downregulated by the tumor microenvironment in all the B-cell malignancies studied (MCL, FL, CLL, and SMZL), suggesting a fundamental role of these 2 specific BH3-only proteins in the microenvironment-dependent survival of lymphoma cells." (PMID 30666297, 2018). "By activating MYC to drive cell proliferation and counteracting MYC-triggered apoptosis by silencing BCL2L11, EBV TFs are manipulating the same pathways that are deregulated in non-viral lymphomas." (PMID 27490482, 2016).
multiple myeloma (16 papers, 2007 to 2025). "Additionally, miR-30a-5p was detected to down-regulate BCL2L11 depending on P65 for aggravating multiple myeloma." (PMID 37187956, 2023).
leukemia (15 papers, 2007 to 2026). A malignant (clonal) hematologic disorder, involving hematopoietic stem cells and characterized by the presence of primitive or atypical myeloid or lymphoid cells in the bone marrow and the blood. "Furthermore, the integrin-mediated adhesion of leukemia cells to fibronectin leads to proteasomal degradation of the pro-apoptotic protein Bim (BCL2 like 11), promoting cell survival and contributing to minimal residual disease and chemoresistance." (PMID 33435150, 2021). "Moreover, oridonin diminishes the expression of miR-17 and miR-20a and triggers cell death in both doxorubicin-sensitive and -resistant leukemia cells via derepressing BCL2L11, a target mRNA of miR-17 and miR-20a." (PMID 33066509, 2020). "Validated targets concentrated on key leukemia-related genes like PTEN, BCL2L11, CDKN1A, CCND1, RB1, E2F1, and TGFBR2." (PMID 42123456, 2026).
non-small cell lung carcinoma (14 papers, 2013 to 2023). A group of at least three distinct histological types of lung cancer, including non-small cell squamous cell carcinoma, adenocarcinoma, and large cell carcinoma. "A germline deletion in the BIM (BCL2L11) gene has been shown to impair the apoptotic response to tyrosine kinase inhibitors (TKIs) in vitro but its association with poor outcomes in TKI-treated non-small cell lung cancer (NSCLC) patients remains unclear." (PMID 28467813, 2017).
neuroblastoma (12 papers, 2008 to 2025). Neuroblastoma (NB) is the most common solid, extracranial childhood tumor. "One interesting study demonstrated that neuroblastomas have increased levels of miR-17-5p, which inhibits p21 and BCL2L11 (a.k.a., BIM) expression, and that p21 downregulation is significant in tumors with MYCN amplification and a poor clinical outcome." (PMID 24212967, 2011).
ovarian carcinoma (12 papers, 2014 to 2023). A malignant neoplasm originating from the surface ovarian epithelium. "The lncRNA HAND2-AS1/miR-340-5p/BCL2L11 axis was shown to promote proliferation and apoptosis of ovarian cancer through the ceRNA mechanism and affect patient survival." (PMID 35910206, 2022). "According to previous reports, BCL2L11 is involved in biological pro-cesses in a variety of solid tumors such as ovarian cancer, endometrial adenocarcinoma, prostate tumor and gastric cancer." (PMID 33845844, 2021). "In this study, repression of miR-25 in ovarian cancer cells enhanced apoptosis by directly targeting Bim (also known as BCL2L11)." (PMID 29765562, 2018). "Moreover, downregulated expression of miR-17~92 contributed to cell cycle arrest in the G2/M phase, suppressed cell growth, and improved the response to PAC by upregulating BCL1-like 11 (BCL2L11, BIM) in ovarian cancer cells." (PMID 34631583, 2021).
chronic myeloid leukemia (11 papers, 2014 to 2026). "Lower expression of BCL2L11 associated with DNA hypermethylation has been observed in chronic myeloid leukaemia." (PMID 29755656, 2018). "BCL2L11 downregulation has a central role in the survival of clonal progenitors of chronic myeloid leukemia (CML), and this low expression was ascribed to DNA hypermethylation at the gene promoter." (PMID 30409182, 2018). "Genetic variations in BCL2L11 mediate the heterogeneity of responses to tyrosine kinase inhibitors in NSCLC and chronic myeloid leukemia." (PMID 38690279, 2024).
colon carcinoma (11 papers, 2013 to 2025). "In HCT-116 colon cancer cells, the combination of butyrate and DHA significantly reduced methylation of genes encoding the proapoptotic Bcl2l11, Cideb, Dapk1, Ltbr, and Tnfrsf2." (PMID 29259973, 2017).
colorectal cancer (11 papers, 2014 to 2025). A primary or metastatic malignant neoplasm that affects the colon or rectum. "For this purpose, the relative expression of CASP3, CASP9, BCL2, and BCL2L11 was quantified in colorectal cancer DLD-1 and SW620 cells treated with 7 mg/mL of the extract for 72 h." (PMID 40298626, 2025). "Overexpression of miR-10b induced resistance to 5-fluorouracil in colorectal cancer cells by targeting BCL2L11." (PMID 24788655, 2014). "mir-10b confers resistance to 5-fluorouracil in colorectal cancer, where it inhibits the pro-apoptotic BH3-only Bcl-2 family member BIM (BCL2L11) and is considered a negative prognostic factor in chemotherapy-treated patients." (PMID 33423689, 2021).
B-cell lymphomas (10 papers, 2011 to 2024). "Interestingly, BCL2L11 is reportedly repressed by miR10a in neurons associated with Parkinson’s disease and by miR17 in B-cell development, highlighting a role for these genes in SC-1 and more generally in B-cell lymphoma." (PMID 37371852, 2023). "The apoptotic activity of BCL2L11 is frequently suppressed in B-cell lymphomas by overexpression of interacting factors like BCL2." (PMID 31141539, 2019). "Downregulation of BCL2L11 by genomic deletion, DNA-methylation or via overexpressed micro-RNAs targeting BCL2L11 represent alternative or additional mechanisms in B-cell lymphomas to escape apoptosis." (PMID 31141539, 2019). "Moreover, the PTEN tumour suppressor and the pro-apoptotic BIM proteins (also known as BCL2-like 11) were identified as relevant targets for miR-19 activity in B-cell lymphoma." (PMID 24145746, 2013).
glioblastoma (10 papers, 2014 to 2025). The most malignant astrocytic tumor (WHO grade IV). "In glioblastoma, m5C modifications of mature miR-181a-5p lead to the loss of its ability to target the mRNA of the pro-apoptotic protein BIM, also known as B-cell chronic lymphocytic leukemia/lymphoma (Bcl-2)-like 11 (BCL2L11)." (PMID 36012529, 2022). "Accordingly, in the TCGA online dataset, low expression levels of BCL2L11/BIM correlate with shorter overall survival of glioblastoma patients." (PMID 26887050, 2016). "miR-92a-3p was increased in glioblastoma and targeted BCL2L11 to reduce tumor apoptosis." (PMID 29127316, 2017). "In glioblastoma-derived cell lines and glioblastoma tumor samples, the methylation of mature miR-181a-5p by the DNMT3A/AGO4 complex inhibits the recognition of its target mRNA BIM, a proapoptotic gene, also known as B-cell chronic lymphocytic leukemia/lymphoma (Bcl-2)-like 11 (BCL2L11)." (PMID 34282776, 2021).
acute lymphoblastic leukemia (9 papers, 2014 to 2023). Leukemia with an acute onset, characterized by the presence of lymphoblasts in the bone marrow and the peripheral blood. "In the acute lymphoblastic leukemia context, different mechanisms of BCL2L11 (BIM) regulation have been identified." (PMID 36229595, 2022). "However, a recent work in acute lymphoblastic leukemia has demonstrated that upon Dex treatment, this specific enhancer promotes an active chromatin interaction with the BCL2L11 promoter to up-regulate gene transcription." (PMID 37524526, 2023).
gastric cancer (9 papers, 2012 to 2025). A primary or metastatic malignant neoplasm involving the stomach. "It was demonstrated that the expression of BCL2L11 decreased in gastric cancer tumor tissues by nearly 70% of that in para-carcinoma tissues." (PMID 40806148, 2025). "For example, it is reported that the expression of BCL2L11 is a direct target of miR-24 in gastric cancer, regulating cell growth and apoptosis." (PMID 33845844, 2021). "For tumor growth, a previous study found that over-expressed miR-24 can promote gastric cancer growth and suppress apoptosis by inhibiting BCL2L11 expression." (PMID 29113415, 2017). "To conclude, we illustrated that an important cell-apoptosis initiator, BCL2L11, is regulated by miR-24 in gastric cancer." (PMID 26758252, 2016). "To give more evidence that miR-24 promotes tumorigenesis in gastric cancer, we used miR-24 mimics and lenti-virus particles to overexpress miR-24 and BCL2L11 in SGC7901 cells simultaneously." (PMID 26758252, 2016). "In this study, miR-24 and BCL2L11 levels showed opposite trends in 6 pairs of gastric carcinoma and para-carcinoma tissues." (PMID 26758252, 2016). "Therefore, miR-24 is most likely to be the important regulator of BCL2L11 in gastric cancer cells." (PMID 26758252, 2016).
prostate carcinoma (9 papers, 2012 to 2023). A carcinoma that arises from epithelial cells of the prostate gland. "The expression of three genes (BCL2L11, PIK3CA, and XIAP) regulated in opposite directions (up/down) occurred in patients with HD and breast/prostate cancer." (PMID 37298337, 2023).
autoimmune disease (8 papers, 2008 to 2025). A disorder resulting from loss of function or tissue destruction of an organ or multiple organs, arising from humoral or cellular immune responses of the individual to their own tissue constituents. "This region has SNP-based associations with a wide range of autoimmune diseases (vitiligo, alopecia areata, multiple sclerosis, systemic lupus erythematosus, and type 1 diabetes), and contains BCL2L11, encoding BIM." (PMID 38562931, 2024). "BCL2L11 encodes BIM, which belongs to the BCL-2 protein family and is crucial for controlling apoptosis, immune homeostasis, and autoimmune diseases." (PMID 33841406, 2021). "The immunopathology seen in Bcl2l11−/−Faslpr/lpr and Bcl2l11+/−Faslpr/lpr mice on this background therefore demonstrates that these two apoptotic pathways have overlapping functions in the prevention of autoimmune disease." (PMID 18275830, 2008). "Knockout mice for BCL2L11 display progressive autoimmune disease." (PMID 39930543, 2025). "An example is the important role of the BH3-only protein BIM (BCL2L11) in lymphocytes, as BIM deletion results in defective thymic selection, and development of lymphoproliferative and autoimmune diseases." (PMID 40150937, 2024).
Autoimmunity (8 papers, 2014 to 2024). The occurrence of an immune reaction against the organism's own cells or tissues. "In fact, increased expression of miR-148a was shown to favor lethal autoimmunity in a lupus mouse model by impairing the B cell tolerance mechanism through suppression of Gadd45a, Pten, and Bcl2l11, key encoders of the pro-apoptotic factor Bim." (PMID 38338832, 2024). "The upregulated miR-148a also targets PTEN, as well as GADD45A and BCL2L11, and it accelerates the development of autoimmunity." (PMID 30658565, 2019). "Three genes, Gadd45a, Bcl2l11, and PTEN, which are implicated in autoimmunity, were identified as miR-148a targets." (PMID 29760712, 2018).
glioma (8 papers, 2015 to 2023). A benign or malignant brain and spinal cord tumor that arises from glial cells (astrocytes, oligodendrocytes, ependymal cells). "Sequencing showed that transcription factor AP-1 and its target gene Bim (Bcl2l11), related to the signaling pathway, played a major role in the apoptosis of glioma after IRE." (PMID 36358391, 2022). "For this purpose, we studied two predicted miR-138 targets for their involvement in TMZ resistance of glioma cells, namely CD166/ALCAM and BCL2L11/BIM." (PMID 26887050, 2016).